GPR68 (G protein-coupled receptor 68)
Diseases named in the same sentence as GPR68 in open-access papers (continued):
Sharing a sentence is not in itself a finding about the gene and the disease.
melanoma (16 papers, 2009 to 2025). A malignant, usually aggressive tumor composed of atypical, neoplastic melanocytes. "Previous studies demonstrated that loss of GPR68 leads to smaller tumor size in male mice in syngeneic melanoma models." (PMID 37350933, 2023). "Studies have shown that host microenvironmental GPR68 deficiency reduced growth of melanoma B16-F10 cell tumors in a syngeneic tumor model using male mice." (PMID 37350933, 2023). "In the present study, for the first time, Gpr68 was found to associate with gender difference in melanoma growth." (PMID 37350933, 2023). "We established a syngeneic melanoma model in Gpr68-deficient mice and investigated tumor growth in males and females." (PMID 37350933, 2023). "This indicates that GPR68 expression inhibited the infiltration of melanoma tissues by CD8+ T cells and NK cells." (PMID 41190345, 2025). "Subcutaneous injection of B16F10 melanoma cells into GRP68-knockout (KO) mice and wild-type (WT) mice revealed that GPR68 knockout reduced melanoma growth, suggesting that GPR68 deficiency in the host cells impedes tumor growth." (PMID 39336742, 2024). "In a B16F10 melanoma mouse model, an acidic tumor microenvironment induced the expression of GPR68 in T cells, attenuated T cell function, and promoted tumor growth." (PMID 39336742, 2024). "We injected mouse melanoma cell line B16-F10 subcutaneously in WT and Gpr68-/- mice of both sexes and monitored the growth of tumor over time." (PMID 37350933, 2023). "GPR68 is also highly expressed in many tumors, such as melanoma, pancreatic ductal adenocarcinoma, colorectal cancer and medulloblastoma." (PMID 37350933, 2023). "This suggests that GPR68 is critical for regulating melanoma growth in vivo and its role is gender dependent." (PMID 37350933, 2023). "Since GPCRs are more feasible to develop small molecule drugs compared to transcription factors, our study demonstrates the potential of GPR68 as a novel druggable therapeutic target for melanoma in male patients." (PMID 37350933, 2023). "As a proton and mechanic dual sensor, GPR68 have been shown to play crucial roles in tumor biology, including promoting melanoma tumorigenesis in male, inducing pancreatic tumor growth via fibroblast activation, and inhibiting prostate tumor metastasis." (PMID 37350933, 2023). "The expression of GPR68 is highly up-regulated in numerous types of cancer, including prostate, colon and pancreatic tumors, melanoma, myelodysplastic syndrome, and medulloblastoma." (PMID 35884475, 2022). "has reported that host Gpr68-deficiency led to increased effector CD8+ T cell number and enhanced T cell proliferation, migration as well as IFNγ, TNFα and GramB production, which is responsible for the impaired melanoma tumor growth in male mice." (PMID 37350933, 2023). "GPR68 is required for melanoma growth in males but dispensable in females." (PMID 37350933, 2023). "Our data suggest that microenvironmental GPR68 is required for melanoma tumor growth in males but dispensable in females, could be due to inhibition of infiltrating CD8+ T cells and NK cells as well as suppression of secretion of IFNγ by those two populations." (PMID 37350933, 2023). "Melanoma B16-F10 cell tumors were significantly smaller in GPR68 KO mice compared to WT mice." (PMID 30696114, 2019). "However, neither loss-of-function nor gain-of-function of Gpr68 in B16-F10 melanoma cell line affected cell proliferation and migration." (PMID 37350933, 2023). "This review summarizes current knowledge regarding GPR68—its expression, regulation, signaling pathways, physiological roles, and functions it regulates in human cancers (including prostate, colon and pancreatic cancer, melanoma, medulloblastoma, and myelodysplastic syndrome)." (PMID 30696114, 2019). "It has also been shown that extracellular acidosis activates the proton-sensing GPR68 and GPR65 to increase the expression of the immune checkpoint PD-L1 in squamous-cell carcinoma (SCC) and B16F10 melanoma cells." (PMID 39336742, 2024).
melanoma (continued). "Here we studied the effect of Gpr68 in a B16-F10 syngeneic melanoma model in both gender and found that tumor growth was repressed in Gpr68-/- male mice not in females." (PMID 37350933, 2023). "GPR68 inhibits infiltration of CD45+ lymphocytes, CD8+ T cells and NK cells in melanoma in male mice, but has no apparent effect in females." (PMID 37350933, 2023). "Moreover, another study showed that GPR68 inhibited the infiltration of CD8+ T cells and natural killer cells in B16F10 melanoma and promoted tumor growth in male mice but not in female mice." (PMID 39336742, 2024).
breast carcinoma (13 papers, 2013 to 2025). "For example, in patients with breast cancer, high GPR68 expression is associated with higher recurrence and mortality rates, which confirms the prognostic potential of GPR68 and provides a basis for individualized treatment plans for patients." (PMID 41190345, 2025). "Association between GPR68 expression and the clinicopathological parameters of breast cancer patients, using data from the in-silico and the recruited cohort in the study." (PMID 35311103, 2022). "Another recent study demonstrated that activation of GPR68 under acidic conditions induced cytoplasmic lipid droplet accumulation and autophagy in breast cancer cells." (PMID 39336742, 2024). "For example, breast cancer cells sense 2-Pa shear stress via GPR68/OGR1 to trigger calcium transients, while 24-Pa pressure inactivates GPCRs to regulate F-actin assembly and YAP activity." (PMID 37864030, 2023). "Depletion of GPR68 inhibited breast cancer cell growth in vitro and tumor formation in vivo." (PMID 39336742, 2024). "In the hepatocellular carcinoma cell line HuH-7 and the breast cancer cell line BT474, weak to moderate GPR68 expression was noted." (PMID 31652823, 2019). "For example, GPR161 is functionally expressed in breast cancer and GPRC5A in pancreatic cancer and GPR68 in the tumor microenvironment." (PMID 32039239, 2019).
pancreatic cancer (11 papers, 2018 to 2025). "GPR68 is a mediator interacting with pancreatic cancer-associated fibroblasts and tumor cells." (PMID 32513106, 2020). "In pancreatic cancer (PC), it was found that the average expression level of GPR68 in 147 patients with PC was 10.5 times higher than that in 165 healthy individuals." (PMID 41190345, 2025). "Recent findings have implicated GPR68 in the pro-oncogenic effects of the TME, with its activity in cancer-associated fibroblasts being critical for tumor growth in pancreatic cancer." (PMID 38291540, 2024). "Similar findings have been described in the literature, and the contribution of GPR68 expression in tumour stroma on cancer growth has been demonstrated in pancreatic cancer." (PMID 31652823, 2019). "GPR68 expression is low in pancreatic cancer cell lines and thus its high expression in PDAC tumors likely reflects expression by cells in the TME other than the cancer cells themselves." (PMID 30696114, 2019). "Interestingly, Lorazepam, a selective GPR68 agonist, increased the expression of IL-6 through GPR68 in human PDAC CAFs and was associated with poor survival outcomes in pancreatic cancer." (PMID 39336742, 2024). "Moreover, clinical evidence indicate that the patients using anxiolytic Lorazepam, which has off-target agonism of GPR68, had a 3.8-fold higher rate of recurrent pancreatic cancer compared to control group." (PMID 38291540, 2024). "Abnormal GPR68 expression is closely associated with chronic inflammation, acidosis, and fibrosis in diseases including osteoarthritis, atherosclerosis, chronic kidney disease, Alzheimer’s disease, Parkinson’s disease, glioblastoma (GBM), and pancreatic cancer." (PMID 41190345, 2025). "Alarmingly, the use of anxiolytic Lorazepam, which has off-target agonism of GPR68, but not alprazolam, which does not activate GPR68, has recently been associated with a 3.8-fold higher rate of pancreatic cancer progression and related death than in non-users." (PMID 38291540, 2024).
asthma (10 papers, 2013 to 2024). "Gpr68 deficient mice exhibit less severe airway inflammation in the ovalbumin-induced experimental asthma model." (PMID 36400753, 2022). "Fittingly, GPR68-deficient mice lack the cardinal features of asthma, including airway eosinophilia and hyperresponsiveness as well as goblet cell metaplasia, in association with substantial inhibition of Th2-related cytokines and IgE production in an ovalbumin-induced asthma model." (PMID 31652823, 2019). "Thus, GPR68 may be involved in airway inflammation and remodelling, e.g., during asthma." (PMID 31652823, 2019).
medulloblastoma (10 papers, 2013 to 2024). A malignant, invasive embryonal neoplasm arising from the cerebellum. "TRPC4-activation by GPR68 agonists promoted the invasion and metastasis of granule precursor-derived human medulloblastoma." (PMID 36046118, 2021). "GPR68 expression has also been detected in human medulloblastoma tumour samples and in the DAOY medulloblastoma cell line and also in these cells a tumour promoting effect was observed." (PMID 31652823, 2019). "GPR68 is highly expressed in human medulloblastoma tissue and medulloblastoma cell line DAOY." (PMID 30696114, 2019). "GPR68 also regulates medulloblastoma cell growth and proliferation and may mediate response to lenalidomide in MDS." (PMID 30696114, 2019). "GPR68 (OGR1) is one of at least four pHo-sensitive G-protein-coupled receptors (GPCRs) and is present in medulloblastoma tissue, rat HC neurons, and rat anterior pituitary gland." (PMID 40161402, 2024).
inflammatory bowel disease (9 papers, 2019 to 2025). A spectrum of small and large bowel inflammatory diseases of unknown etiology. "In inflammatory bowel disease patients, GPR68 expression is also significantly increased in macrophages and monocytes." (PMID 41190345, 2025). "RNA-seq analysis showed GPR68 is robustly expressed in Trpv1+ colonic nociceptors and upregulated in tissue from people with inflammatory bowel disease, consistent with reduced disease activity in DSS-treated GPR68-/- mice." (PMID 41197770, 2025). "In the terminal ileum of inflammatory bowel diseases, the expression of OGR1/GPR68 positively increases the expression of pro-fibrotic genes and collagen deposition, suggesting the potential involvement of these receptors, signaling for the pathogenesis of DN." (PMID 31212704, 2019). "The activity and expression of GPR68 was significantly increased in inflammatory bowel disease." (PMID 38347610, 2024).
glioblastoma (8 papers, 2019 to 2026). The most malignant astrocytic tumor (WHO grade IV). "Previously, we showed that Ogremorphin (OGM), a specific GPR68 inhibitor, induced ferroptosis in glioblastoma multiforme (GBM) cells." (PMID 42211518, 2026). "In glioblastoma, GPR68 supports a prosurvival ATF4 pathway; Ogremorphin-mediated inhibition drives lipid peroxidation, iron-dependent cell death, and sensitization to radiotherapy." (PMID 41595528, 2026). "By facilitating the release of ATP and the surface exposure of calreticulin, ferroptosis inducers like Erastin, which targets Xc-, and Ogremorphin, which targets GPR68, provide a promising avenue for enhancing the efficacy of immunotherapies in glioblastoma." (PMID 40756273, 2025). "We used U87 glioblastoma cells, which highly express GPR68, to generate clones that stably expressed pHluorin2-GPI under a ubiquitous promoter." (PMID 38291540, 2024). "Using this drug class and genetic means, we demonstrate that GPR68 mediates a critical pro-survival pathway activated in glioblastoma cells in an autocrine manner by the acidic extracellular milieu." (PMID 38291540, 2024). "Ogremorphin has been shown to block GPR68-dependent migration and metastasis of cancer cells, and more recent work indicates that GPR68 inhibition using Ogremorphin or related compounds can induce ferroptosis and radiosensitization in glioblastoma and other tumor models." (PMID 41595528, 2026). "Moreover, we show that genetic and pharmacological disruption of GPR68 signaling in glioblastoma cells induces ferroptosis, an iron-mediated cell death program, across a diverse set of GBM lines." (PMID 38291540, 2024). "Furthermore, in one case of glioblastoma, accumulation of GPR68-positive granulocytes was observed." (PMID 31652823, 2019). "We used a pHLourin2 probe to demonstrate how glioblastoma cells acidify their microenvironment to activate the commonly over expressed acid sensing GPCR, GPR68." (PMID 38291540, 2024). "It has also been shown that blocking GPR68 increases ATF4 expression and ferroptotic cell death in glioblastoma cells." (PMID 39336742, 2024). "Recent studies have shown that the activation of GPR68 under acidic conditions activates the endoplasmic reticulum stress activating transcription factor 4 (ATF4) signaling pathway, which is a novel survival pathway in glioblastoma." (PMID 41190345, 2025). "Using our small molecule inhibitor OGM and genetic means, we show that blocking GPR68 signaling results in robust cell death in all thirteen glioblastoma cell lines tested, irrespective of genetic and phenotypic heterogeneity, or resistance to the mainstay GBM chemotherapeutic temozolomide." (PMID 38291540, 2024).
chronic kidney disease (6 papers, 2021 to 2026). Impairment of the renal function secondary to chronic kidney damage persisting for three or more months. "Among these pathways, G protein-coupled receptor 68, a proton- and flow-sensitive G protein-coupled receptor, is discussed as a representative druggable node linking mechanical and inflammatory signaling in chronic kidney disease-associated cardiac injury." (PMID 42074080, 2026). "It was also determined in another study that GPR68 can promote cardiac inflammation and fibrosis in a chronic kidney disease (CKD) model." (PMID 39336742, 2024). "In support of our results, recent studies have identified GPR68 as a mediator of intestinal inflammation and cardiac inflammation under chronic kidney disease conditions." (PMID 39768215, 2024). "As observed in 5/6Nx mice, the expression of GPR68 in transplanted monocytes of Splx-5/6Nx mice was also induced by humoral factors in the blood whose levels likely increase during chronic renal failure." (PMID 33986294, 2021). "However, the cardiac-infiltrated high-GPR68-expressing monocytes in 5/6Nx mice may have been activated by factors rather than the decrease in pH, because it is unlikely to cause myocardial ischemia and local acidosis during chronic renal failure." (PMID 33986294, 2021). "An evaluation for the underlying mechanism of attenuation of cardiac inflammation and fibrosis in 5/6Nx mice leads to the identification of the monocytic expression of G protein-coupled receptor 68 (GPR68) as a key molecule exacerbating cardiac function during chronic renal failure." (PMID 33986294, 2021). "Therefore, the accumulation of retinol and RBP4 in the serum during chronic renal failure induces GPR68 expression in monocytes." (PMID 33986294, 2021). "For example, in chronic kidney disease (CKD), the increased expression of GPR68 on human monocytes promotes the release of TNF-α, IL-6, and other pro-inflammatory cytokines, which aggravate systemic inflammation and fibrosis." (PMID 41190345, 2025).
colon carcinoma (6 papers, 2017 to 2024). "We propose that highly expressed GPCRs in cancer cells (for example, GPRC5A in PDAC and colon cancer cells and GPR68 in PDAC CAFs) may contribute to the malignant phenotype, serve as biomarkers and/or may be novel therapeutic targets for the treatment of cancer." (PMID 29872392, 2018).
idiopathic pulmonary fibrosis (6 papers, 2021 to 2024). Idiopathic pulmonary fibrosis (IPF) is a nonneoplastic pulmonary disease that is characterized by the formation of scar tissue within the lungs in the absence of any known cause. "GPR68 protein levels were reduced in idiopathic pulmonary fibrosis (IPF) patient lung tissues compared to healthy controls." (PMID 39336742, 2024). "Ongoing work investigating the effect of Ogerin in the pulmonary epithelium and the potential of Ogerin to inhibit pulmonary fibrosis in vivo will expand our understanding of GPR68 in normal and pathological states." (PMID 35901086, 2022).
amelogenesis imperfecta (5 papers, 2016 to 2025). Amelogenesis imperfecta (AI) represents a group of developmental conditions affecting the structure and clinical appearance of the enamel of all or nearly all the teeth in a more or less equal manner, and which may be associated with morphologic or biochemical changes elsewhere in the body. "A recent observation reported that a homozygous loss of function of GPR68 was described in families with amelogenesis imperfecta, which suggests that GPR68 is required for dental enamel formation." (PMID 40563452, 2025). "We identified rare homozygous variants in GPR68 in three families with amelogenesis imperfecta, a genetically and phenotypically heterogeneous group of inherited conditions associated with abnormal enamel formation." (PMID 27693231, 2016). "Furthermore, a GPR68 HKO reported Amelogenesis imperfecta distinctive clinical manifestations." (PMID 33727708, 2021).
colorectal cancer (5 papers, 2017 to 2024). A primary or metastatic malignant neoplasm that affects the colon or rectum. "CAFs in PDAC, GIST, appendiceal and colorectal cancers also express GPR68; in PDAC, CAF-expressed GPR68 regulates pro-inflammatory cytokine production and promotes tumor growth." (PMID 30696114, 2019). "Finally, in their in vivo studies, MC-38 murine colorectal carcinoma cells were injected into WT and GPR68 KO mice." (PMID 36902589, 2023). "Co-culture of human colorectal carcinoma HCT116 cells with human colon fibroblast CCD-18Co cells in 3D spheroid microtumor structures activated CCD-18Co cells to CAFs with a gene signature similar to patient CAFs, among which GPR68 was one of the most highly up-regulated genes during this process." (PMID 30696114, 2019).
pancreatic ductal adenocarcinoma (5 papers, 2019 to 2023). An infiltrating adenocarcinoma that arises from the epithelial cells of the pancreas. "GPR68 expression has been investigated across cancer types including skin, head and neck squamous cancer as well as pancreatic ductal adenocarcinoma." (PMID 35311103, 2022). "GPR68 is nearly undetectable in the healthy pancreas but is highly expressed in pancreatic ductal adenocarcinoma (PDAC)." (PMID 31236404, 2019). "Emerging evidence has revealed that GPR68 may play crucial roles in the biology of pancreatic ductal adenocarcinoma (PDAC)." (PMID 35884475, 2022).
prostate tumor (5 papers, 2016 to 2023). "Whereas genes associated with factors suppressing prostate tumor growth and metastasis like Klf9, and Gpr68 were decreased in MLL- vs. AT1-LNs." (PMID 28472073, 2017).
Acidosis (4 papers, 2015 to 2026). Abnormal acid accumulation or depletion of base. "Acidosis-induced GPR68 signaling in primary fibroblasts has been shown to drive inositol phosphate production, RhoA activation, and cytoskeletal remodeling." (PMID 41595528, 2026). "Acidosis is known to activate these same pathways through GPR68 in non-joint systems: mild decreases in pHe stimulate Gq/11-PLC-Ca2+ signaling and MAPK activation in airway smooth muscle and intestinal epithelial cells." (PMID 41595528, 2026). "Acidosis activates a family of proton sensing G-protein coupled receptors, including G-protein coupled receptor 4 (GPR4), G-protein coupled receptor 65 (GPR65), G-protein coupled receptor 68 (GPR68), and G-protein coupled receptor 132 (GPR132)." (PMID 25988385, 2015).